PROC (protein C, inactivator of coagulation factors Va and VIIIa)
Description:
Protein C is a vitamin K-dependent serine protease that regulates blood coagulation by inactivating factors Va and VIIIa in the presence of calcium ions and phospholipids. Exerts a protective effect on the endothelial cell barrier function.
Synonyms: APC; PC; PROC1; THPH3; THPH4
Tractability: Small molecule: a structure with a bound ligand is known; a high-quality ligand is known; it has a binding pocket of medium quality; it belongs to a druggable protein family. Antibody: UniProt places it where antibodies can reach, with high confidence; its Gene Ontology location is reachable by antibodies, with high confidence; UniProt predicts a signal peptide or a membrane-spanning region. PROTAC: its protein half-life has been measured; a small molecule that binds it is known. Other modalities: an approved drug acts on it.
Target class: Serine protease; Enzyme; Serine protease PA clan; Serine protease S1A subfamily; Protease
Gene: Protein-coding gene on chromosome 2 (127,415,933 to 127,429,762, forward strand). Ensembl gene ENSG00000115718.
Subcellular location: Secreted; Golgi apparatus; Endoplasmic reticulum
Pathways (Reactome):
Metabolism of proteins: Gamma-carboxylation of protein precursors; Post-translational protein phosphorylation; Regulation of Insulin-like Growth Factor (IGF) transport and uptake by Insulin-like Growth Factor Binding Proteins (IGFBPs); Removal of aminoterminal propeptides from gamma-carboxylated proteins; Transport of gamma-carboxylated protein precursors from the endoplasmic reticulum to the Golgi apparatus
Hemostasis: Amplification and propagation of coagulation cascade; Cell surface interactions at the vascular wall; Fibrin formation; Regulation of clotting cascade
Disease: Defective cleavage of FV variant at R334; Defective cleavage of FV variant at a.a.534
Gene Ontology:
Molecular function: protein binding; serine-type endopeptidase activity; calcium ion binding; endopeptidase activity
Biological process: negative regulation of apoptotic process; negative regulation of coagulation; negative regulation of inflammatory response; positive regulation of establishment of endothelial barrier; blood coagulation; negative regulation of blood coagulation; proteolysis
Cellular component: endoplasmic reticulum; extracellular region; Golgi apparatus; endoplasmic reticulum lumen; Golgi lumen
Genetic constraint (gnomAD): Loss-of-function variants: 23 observed, 36.47 expected, observed/expected ratio (o/e) 0.63, 90% interval 0.45 to 0.89. The upper end of that interval is the gene's LOEUF score, 0.89, which puts it in group 3 of 6, group 1 being the genes least tolerant of losing a copy. Missense variants: 526 observed, 637.89 expected, observed/expected ratio (o/e) 0.82, 90% interval 0.77 to 0.89. Synonymous variants: 218 observed, 243.78 expected, observed/expected ratio (o/e) 0.89, 90% interval 0.8 to 1.
Gene-disease validity (ClinGen):
ClinGen rates the evidence that PROC causes each of these diseases.
hereditary thrombophilia due to congenital protein C deficiency (semidominant): Definitive. Congenital protein C deficiency is an inherited coagulation disorder characterized by deep venous thrombosis symptoms due to reduced synthesis and/or activity levels of protein C.
Homologues: Orthologues: chimpanzee PROC (99% identical), macaque PROC (96% identical), dog PROC (80% identical), pig PROC (75% identical), guinea pig PROC (70% identical), rat Proc (69% identical), tropical clawed frog proc (50% identical), zebrafish proca (44% identical), Drosophila melanogaster CG9672 (14% identical). Paralogues in human: PROZ (29% identical).
Diseases named in the same sentence as PROC in open-access papers:
PROC is named in the same sentence as 96 diseases in open-access papers, as found by Europe PMC text mining. Sharing a sentence is not in itself a finding about the gene and the disease. The quoted sentences say what the papers report.
Sepsis (103 papers, 2005 to 2025). Sepsis is defined as life-threatening organ dysfunction caused by a dysregulated host response to infection. "One notable example of decreased gene expression in sepsis was PROC (Protein C), a key regulator of fibrin clot formation." (PMID 25538794, 2014).
thrombophilia (23 papers, 2006 to 2025). A condition characterized by an abnormally high level of thrombi. "Inherited thrombophilia (e.g., venous thromboembolism, VTE) is due to rare loss-of-function mutations in anticoagulant factors genes (i.e., SERPINC1, PROC, PROS1), common gain-of-function mutations in procoagulant factors genes (i.e., F5, F2), and acquired risk conditions." (PMID 34207366, 2021).
Venous thrombosis (12 papers, 2006 to 2026). Formation of a blood clot (thrombus) inside a vein, causing the obstruction of blood flow. "Notably, individuals carrying combined mutations in the SERPINC1 and PROC genes have a significantly higher risk of venous thrombosis." (PMID 41839631, 2026).
COVID-19 (9 papers, 2021 to 2024). A disease caused by infection with severe acute respiratory syndrome coronavirus 2. "The most convincing evidence for association with severe COVID-19 was found for five loci: two folate metabolic genes (MTHFR and MTR), two hemostasis inhibitor genes (PROC and ADAMTS13), and a thrombospondin gene (THBS2)." (PMID 34834519, 2021). "Conversely, components of the coagulation cascade (SERPINA5, SERPIND1, PROC, CPB2, F13B, and KLKB1) and proteins involved in cholesterol metabolism were downregulated with the severity of COVID-19 but increased over time." (PMID 35958562, 2022). "We found that PROC, S1PR1, and THBD were downregulated in the nasal epithelium of patients with COVID-19." (PMID 36560757, 2022). "The change in transcription of PROC and the activator receptors PROCR, FR2, and THBD in patients with COVID-19 suggests impaired cytoprotection and progression to the hypercoagulable state." (PMID 36560757, 2022).
Stroke (8 papers, 2015 to 2024). Sudden impairment of blood flow to a part of the brain due to occlusion or rupture of an artery to the brain. "Using public drug databases, we curated drugs targeting those proteins in a direction compatible with a beneficial therapeutic effect against stroke based on MR estimates and identified such drugs for VCAM1, F11, KLKB1, GP1BA, LAMC2 (inhibitors) and PROC (activators)." (PMID 36180795, 2022).
thrombosis (7 papers, 2009 to 2025). "Rare mutations in PROC, PROS1 or SERPINC1 as well as common variants in F5, F2, F11 and SERPINC1 have been identified as risk factors for deep vein thrombosis (DVT)." (PMID 26982741, 2016).
pulmonary embolism (5 papers, 2006 to 2023). The obstruction of the pulmonary artery or one of its branches by an embolus, sometimes associated with infarction of the lung. "We describe a patient with a novel mutation in the PROC gene who was diagnosed with pulmonary embolism in a Chinese family." (PMID 36281079, 2022). "Pulmonary embolism may be caused by protein C deficiency and the rare compound heterozygous mutation in intron 3 of the PROC gene could cause protein C deficiency via impairment of the secretory activity of protein C." (PMID 36281079, 2022).
breast carcinoma (3 papers, 2013 to 2023). "Other researches show that activated PROC-PROCR-F2R axis can stimulate the MAPK pathway via activation of epidermal growth factor receptor (EGFR) to promote the progression of breast cancer." (PMID 37274740, 2023).
Purpura Fulminans (3 papers, 2019 to 2020). A severe, rapidly fatal reaction occurring most commonly in children following an infectious illness. "In those cases, purpura fulminans and thrombosis were the main symptoms, and homozygous or compound heterozygous mutations of the PROC gene were identified." (PMID 31592240, 2019). "These patients have one allele or double allele mutations of PROC, and develop hemorrhagic infarction and/or purpura fulminans within two weeks after birth, although thrombotic trend depends on the absolute PC activity levels." (PMID 30353081, 2019).
gastric cancer (2 papers, 2021 to 2023). A primary or metastatic malignant neoplasm involving the stomach. "However, at present, there is not much research on PROC gene in gastric cancer, so we predict that this gene may be associated with gastric cancer." (PMID 37274740, 2023).
Obesity (2 papers, 2022 to 2025). Accumulation of substantial excess body fat. "Some others, such as SERPINC1, coagulation factor XII (involved in contact activation pathways), and protein C (PROC), are involved in the coagulation/fibrinolysis pathways, which are known to be activated in OA, as well as in obesity." (PMID 35606786, 2022).
protein c deficiency (2 papers, 2024 to 2026). Protein C deficiency is a disorder that increases a person's risk to develop abnormal blood clots due to a deficiency of the Protein C, a protein in the body that prevents blood clotting. "Mutations in the PROC gene leading to protein C deficiency, as well as those in the JAK2 gene, had been shown to be specifically associated with CVT." (PMID 38886735, 2024).
anaphylaxis (1 paper, 2021). An acute hypersensitivity reaction that occurs from exposure to an allergen. "Other protein related with coagulation processes have been found increased in EC-anaphylaxis: PROC, PROS, APOH, Galectin-3 and TSP1." (PMID 34248989, 2021).
Budd-Chiari syndrome (1 paper, 2013). "Therefore, we believe that familial screening for PROC mutations could avoid new thrombotic complications as well as improving the long term prognosis of the patients with Budd-Chiari syndrome caused by protein C deficiency." (PMID 24250338, 2013).
Thromboembolism (1 paper, 2025). The formation of a blood clot inside a blood vessel that subsequently travels through the blood stream from the site where it formed to another location in the body, generally leading to vascular occlusion at the distant site. "This pharmacological potentiation of coagulation worked in concert with the patient's underlying PROC gene mutation, creating a particularly severe thrombogenic milieu that predisposed to the development of multi-system thromboembolism." (PMID 40970186, 2025).
thrombotic disorders (1 paper, 2025). "Thrombotic disorders commonly involved mutations in PROC (27%), PROS1 (12%), SERPINC1 (9%), ADAMTS13 (5%), and JAK2 (3%)." (PMID 40488813, 2025).
uremia (1 paper, 2024). A clinical syndrome associated with the retention of renal waste products or uremic toxins in the blood. "One point to note, in addition to PROC gene mutations, circulating levels of PC may be reduced in several conditions, such as DIC, infection, uremia, cancer or cancer therapy and some autoantibodies." (PMID 38886735, 2024).
infection (8 papers, 2008 to 2025). The state of being infected such as from the introduction of a foreign agent such as serum, vaccine, antigenic substance or organism. "A combination of the three reference genes, proC, recA and ffh, allowed for the accurate expression analysis of amsB and hrpN genes and the calculation of their fold change in E. amylovora after its infection of susceptible and resistant apple cultivars." (PMID 28515453, 2017). "Gene deletion was possible only for three proline biosynthesis genes, proB, proA, and proC, the last of which was upregulated 29-fold during infection." (PMID 36453908, 2022). "Importantly, we observed that among the studied pro genes, the proC gene was the most upregulated during the infection of J774A.1 cells." (PMID 36453908, 2022). "PROC, which encodes anticoagulant protein C, an anti-inflammatory molecule which supresses cytokine production and secretion had the greatest induction (15–23 fold, P<0.01), irrespective of infection." (PMID 26133770, 2015). "In the 72 h infection group, the mRNA expression was up-regulated and the protein expression was down-regulated in 7 groups, namely the TNXB, NFIA, PROC, SPIN1, NR2C2 nuclear receptor subfamily 2 group C member 2, Carboxypeptidase D and ARHGAP11B." (PMID 36496794, 2022). "In the 72 h infection group, the mRNA expression was up-regulated and the protein expression was down-regulated in seven groups, namely the TNXB, NFIA, PROC, SPIN1, NR2C2 nuclear receptor subfamily 2 group C member 2, Carboxypeptidase D and ARHGAP11B." (PMID 36496794, 2022).
cardiovascular diseases (1 paper, 2007). "We investigated the role of four thrombosis genes: coagulation factor V (F5), intercellular adhesion molecule 1 (ICAM1), protein C (PROC), and thrombomodulin (THBD) in cardiovascular diseases." (PMID 17677000, 2007).
genetic disorder (1 paper, 2021). "Hereditary Protein C (PC) deficiency is a rare genetic disorder caused by PROC gene mutation." (PMID 33761690, 2021).
PROC also shares sentences with these, for which no sentence is quoted: coagulopathy (6 papers); tumor (6); atherosclerosis (5); cancer (5); venous thromboembolism (5); hyperhomocysteinemia (4); ischemic stroke (4); systemic lupus erythematosus (4); acute respiratory distress syndrome (3); endothelial dysfunction (3); hereditary thrombophilia (3); lung injury (3); acute kidney injury (2); acute lung injury (2); antiphospholipid syndrome (2); Arterial thrombosis (2); diabetes (2); epilepsy (2); hemophilia A (2); ischemia (2); malaria (2); multiple myeloma (2); myocardial infarction (2); septic shock (2); acute pancreatitis (1); Airway obstruction (1); Alzheimer disease (1); antithrombin deficiency (1); asthma (1); atrial fibrillation (1).
A further 46 diseases each share a sentence with PROC in 1 paper.